MTCL2 (microtubule crosslinking factor 2)
Description:
Microtubule-associated factor that enables integration of the centrosomal and Golgi-associated microtubules on the Golgi membrane, supporting directional migration. Preferentially acts on the perinuclear microtubules accumulated around the Golgi. Associates with the Golgi membrane through the N-terminal coiled-coil region and directly binds microtubules through the C-terminal domain (By similarity). Required for faithful chromosome segregation during mitosis. Regulates autophagy by playing a role in the reduction of glucose production in an adiponectin- and insulin-dependent manner (By similarity).
Synonyms: C20orf117; KIAA0889; SOGA; SOGA1; dJ132F21.1; FLJ44670
Tractability: Antibody: UniProt places it where antibodies can reach, with medium confidence; its Gene Ontology location is reachable by antibodies, with medium confidence. PROTAC: ubiquitination databases record sites on it.
Gene: Protein-coding gene on chromosome 20 (36,777,447 to 36,863,538, reverse strand). Ensembl gene ENSG00000149639.
Subcellular location: Cytoplasm, cytoskeleton; Golgi apparatus membrane; Midbody; Secreted (C-terminal 80 kDa form)
Subcellular location (Human Protein Atlas): Cytosol; Nucleoli; Predicted to be secreted
Gene Ontology:
Molecular function: protein binding
Biological process: chromosome segregation; insulin receptor signaling pathway; negative regulation of gluconeogenesis; regulation of autophagy
Cellular component: extracellular exosome; extracellular region; microtubule; midbody; Golgi membrane; cytoskeleton
Genetic constraint (gnomAD): Loss-of-function variants: 62 observed, 122.62 expected, observed/expected ratio (o/e) 0.51, 90% interval 0.41 to 0.62. The upper end of that interval is the gene's LOEUF score, 0.62, which puts it in group 2 of 6, group 1 being the genes least tolerant of losing a copy. Missense variants: 1,919 observed, 2,078.2 expected, observed/expected ratio (o/e) 0.92, 90% interval 0.89 to 0.96. Synonymous variants: 940 observed, 882.61 expected, observed/expected ratio (o/e) 1.07, 90% interval 1.01 to 1.12.
Homologues: Orthologues: chimpanzee MTCL2 (99% identical), macaque MTCL2 (98% identical), dog MTCL2 (93% identical), pig MTCL2 (93% identical), rat Mtcl2 (92% identical), mouse Mtcl2 (91% identical), guinea pig MTCL2 (79% identical), tropical clawed frog mtcl2 (59% identical), rabbit MTCL2 (56% identical), zebrafish mtcl2 (49% identical), zebrafish mtcl3a (7% identical). Paralogues in human: MTCL1 (39% identical), MTCL3 (18% identical).
Diseases named in the same sentence as MTCL2 in open-access papers:
MTCL2 is named in the same sentence as 10 diseases in open-access papers, as found by Europe PMC text mining. Sharing a sentence is not in itself a finding about the gene and the disease.
MTCL2 shares sentences with these, for which no sentence is quoted: colorectal cancer (3 papers); tumor (3); cancer (2); lymph node metastasis (2); bladder cancer (1); breast carcinoma (1); glioblastoma (1); hepatocellular carcinoma (1); hyperlipidemia (1); virus infection (1).